MIR19B1 (microRNA 19b-1)
Synonyms: hsa-mir-19b-1; C13orf25; MIR19B; MIRH1; MIRHG1; MIRN19B1; miR-19b-1; miRNA19B1
Gene: MicroRNA gene on chromosome 13 (91,351,192 to 91,351,278, forward strand). Ensembl gene ENSG00000284375.
Gene Ontology:
Biological process: miRNA-mediated post-transcriptional gene silencing
Cellular component: RISC complex
Homologues: Orthologues: chimpanzee ptr-mir-19b-1 (100% identical), guinea pig MIR19B1 (95% identical), mouse Mir19b-1 (92% identical), rat Mir19b1 (92% identical), rabbit MIR19B1 (89% identical), zebrafish dre-mir-19b (72% identical), tropical clawed frog xtr-mir-19b-2 (71% identical), tropical clawed frog xtr-mir-19a (59% identical), zebrafish dre-mir-19a (55% identical). Paralogues in human: MIR19B2 (79% identical), MIR19A (59% identical).
Diseases named in the same sentence as MIR19B1 in open-access papers:
MIR19B1 is named in the same sentence as 2 diseases in open-access papers, as found by Europe PMC text mining. Sharing a sentence is not in itself a finding about the gene and the disease.
MIR19B1 shares sentences with these, for which no sentence is quoted: lung carcinoma (1 paper); tumor (1).